OTC (ornithine transcarbamylase)
Diseases named in the same sentence as OTC in open-access papers (continued):
Sharing a sentence is not in itself a finding about the gene and the disease.
cancer (21 papers, 2017 to 2026). A tumor composed of atypical neoplastic, often pleomorphic cells that invade other tissues. "Another arginine degrading enzyme used for cancer therapy is arginase I. Previous studies have suggested that cancers with deficiencies in either ASS and/or OTC expression are sensitive to arginine-auxotrophy induced by arginase I." (PMID 33510635, 2020). "Whatever the benefit, OTC downregulation renders cancer cells sensitive to treatment with human arginase, independently of ASS1 expression." (PMID 30108309, 2018). "Decreasing OTC expression facilitates the diversion of ornithine into alternative metabolic pathways, including polyamine biosynthesis, which promotes the survival of cancer cells." (PMID 40710547, 2025). "The ASS1 and OTC negativity could also serve as predictive biomarkers for the response in other arginine-dependent cancers." (PMID 39570001, 2024). "However, cancer cells may be dependent on extracellular arginine for survival—arginine auxotrophism, due to the loss of ASS or OTC recycling enzyme expression; making them vulnerable to therapeutic arginine depletion." (PMID 29168171, 2018). "Thus, arginine depletion could be a potential therapeutic approach for malignant tumors, and the arginine biosynthesis key enzyme OTC and ASS were considered as effective and sensitive indicators in the arginine depletion therapy." (PMID 28358368, 2017). "In cancer cells, the UC is reconfigured/reorchestrated to support high anabolic demand, often involving the dysregulation of key enzymes such as ASS1, ASL, OTC and CPS1." (PMID 42074106, 2026). "As the cellular expression of OTC seems less commonly observed in tumors than the expression of ASS, both ADC and arginase are likely to be of considerable value in future cancer treatment." (PMID 37762044, 2023). "Depletion of arginine induced by PEGylated arginase 1 (ARG1) (BCT-100) has shown anticancer effects in arginine auxotrophic cancers that lack argininosuccinate synthetase (ASS1) and ornithine transcarbamylase (OTC)." (PMID 30808864, 2019). "Pegylated arginine deiminase targets cancer cells defective in ASS1 expression, while pegylated arginase I targets a broader spectrum of cancer cells, which are defective in OTC and/or ASS1 expression." (PMID 28750681, 2017). "On top of all these engineering issues, many cancer cells are argininosuccinate synthase (ASS)-positive but ornithine transcarbamylase (OTC)-negative, meaning that they are intrinsically resistant to ADI-PEG20." (PMID 32545874, 2020). "However, defects in the expression of the arginine recycling enzymes ornithine transcarbamylase (OTC) and argininosuccinate synthetase (ASS) can result in a dependence of cancer cells on extracellular sources of arginine for survival." (PMID 29776373, 2018). "ADI and BCT-100 were pre-clinically and clinically proven to inhibit arginine auxotrophic tumors with ADI targeting ASS1 deficient cancers and BCT-100 targeting ASS1 and/or OTC negative cancers." (PMID 28464918, 2017). "However, some arginine-auxotrophic cancer cells cannot autonomously synthesize arginine due to lacking of argininosuccinate synthetase 1 (ASS1) or ornithine transcarbamylase (OTC)." (PMID 41460862, 2025). "Notably, reduced OTC expression has been reported in patient samples of HCC, suggesting a potential mechanism by which cancer cells may adapt to their metabolic environment." (PMID 40710547, 2025). "Both downregulated CPS1 activity (CRhi NSCLC and intrahepatic cholangiocarcinoma tumors) or OTC activity (CRhi HCC tumors) result in severe arginine auxotrophy and therefore reflect a common repression of mitochondrial urea cycle metabolism in these different cancer subtypes." (PMID 35838048, 2022).
metabolic disease (13 papers, 2021 to 2025). A congenital disorder (due to inherited enzyme abnormality) or acquired (due to failure of a metabolically important organ) disorder resulting from an abnormal metabolic process. "BACKGROUND: Ornithine transcarbamylase deficiency (OTCD) is a rare hereditary metabolic disorder caused by mutations in the OTC gene." (PMID 41123737, 2025). "We found one case of reported mutism related to a metabolic disorder (ornithine transcarbamylase deficiency)." (PMID 37140666, 2023). "The smooth long‐run gene transfer into the liver can manage diverse plasma protein insufficiency problems and metabolic diseases including ornithine transcarbamylase deficiency." (PMID 37469226, 2023). "Ornithine transcarbamylase (OTC) deficiency is the most common inherited metabolic disorder in urea cycles with an incidence of 1:14,000 live births." (PMID 35204506, 2022). "In 1999, the University of Pennsylvania conducted a clinical trial for an adenovirus serotype 5 (Ad5)-based gene therapy for a rare metabolic disease known as ornithine transcarbamylase (OTC)." (PMID 38247731, 2024). "We apply this approach to improve the potency of ornithine transcarbamylase (OTC), a urea cycle enzyme for which loss of catalytic activity causes a rare but serious metabolic disease." (PMID 35087131, 2022).
genetic disorder (5 papers, 2020 to 2024). "Ornithine transcarbamylase (OTC) deficiency is the most common genetic disorder of the urea cycle." (PMID 37854728, 2023).
infection (4 papers, 2014 to 2023). The state of being infected such as from the introduction of a foreign agent such as serum, vaccine, antigenic substance or organism. "The infection is caused by Pseudomonas syringae pathovars that produce phaseolotoxin, an antimetabolite which targets arginine metabolism, particularly by inhibition of ornithine transcarbamylase (OTC)." (PMID 38179474, 2023). "The amount of OTC tended (P=0.086) to be reduced in WT littermates during infection, whereas OTC protein levels remained unchanged in the spf-ash mice." (PMID 24271778, 2014). "Transcriptional repression of Otc and Ass1 manifested in reduced abundance of OTC and ASS1 proteins in hepatocytes as observed by immunohistochemistry on days 2 and 8 after infection." (PMID 31784108, 2019). "In line with the IFNAR1-dependent increase of systemic ornithine levels upon infection, these data indicate that IFNAR1 represses the degradation of ornithine via OTC in hepatocytes." (PMID 31784108, 2019). "During infection, CPS1 activity decreased by 40% (P=0.001) in WT and 28% (P=0.018) in spf-ash, whereas OTC activity decreased by 7% (P=0.005) in WT and 21% (P=0.015) in spf-ash." (PMID 24271778, 2014).
autosomal dominant disease (1 paper, 2011). Autosomal dominant form of disease.
OTC also shares sentences with these, for which no sentence is quoted: Hyperornithinemia (4 papers); propionic acidemia (4); Argininemia (3); glutaric acidemia type I (3); Hepatic failure (3); retinitis pigmentosa (3); tyrosinemia type I (3); (MCAD) deficiency (2); argininosuccinate lyase deficiency (2); attention deficit-hyperactivity disorder (2); biliary atresia (2); breast carcinoma (2); galactosemia (2); intrahepatic cholestasis (2); systemic inflammatory response syndrome (2); X-linked intellectual disability (2); Acute encephalopathy (1); acute lymphoblastic leukemia (1); Adult onset (1); alcohol use disorder (1); Alexander disease (1); alpha 1-antitrypsin deficiency (1); antiphospholipid syndrome (1); arginase deficiency (1); autism spectrum disorder (1); autoimmune hepatitis (1); Batten disease (1); bipolar disorder (1); Bladder Cancer (1); blastoma (1).
A further 80 diseases each share a sentence with OTC in 1 paper.